MMP14 (matrix metallopeptidase 14)
Diseases named in the same sentence as MMP14 in open-access papers (continued):
Sharing a sentence is not in itself a finding about the gene and the disease.
tumor (continued). "MMP14 activity mediated proteolytic processing to activate HB-EGF, stimulating the EGFR signaling pathway to increase proliferation and promote tumor growth." (PMID 36656313, 2023). "Further, major MMPs involved in promoting tumor angiogenesis, which is an important step for tumor vascularization and also represents an avenue for metastasis, include MMP-2, MMP-9 and MMP-14." (PMID 37091337, 2023). "COL12A1+ fibroblasts highly expressed MMP2, MMP14, and TGFB1, which are related to tumor cell invasion and ECM degradation." (PMID 37430270, 2023). "In particular, MMP14 can control the formation of invasive pseudopodia, while MMP2 and MMP9 play a key role in tumor invasion." (PMID 37686118, 2023). "Regarding the protein levels of these genes, SLC2A1, MMP14, TOP2A, ANLN, and SLC22A3 exhibited higher expression in tumor samples compared to normal samples." (PMID 37604837, 2023). "As demonstrated by our findings, ECM-modulating genes, such as MMP2 and MMP14, were clearly upregulated in the CAFs, and CAFs were found to secrete PDGFRA and CXCL12, which promote tumor progression, further validate the accuracy of CAF classification." (PMID 37565899, 2023). "Invasive pseudopodia can recruit the proteases MMP-9 and MMP-14 to the leading edge, where they degrade ECM and basement membrane, thereby promoting tumor invasion and metastasis." (PMID 37670313, 2023). "The family of matrix metalloproteinases (MMPs) is also involved in various physiological processes such as inflammation, cancer, and wound healing; among them, MMP14 and MMP3 are involved in tumor progression." (PMID 37960213, 2023). "Another in vitro study on mouse corticotrope tumor cells demonstrated that matrix metalloproteinase-14 (MMP14) overexpression is correlated with VEGF overexpression and that the inhibition of MMP14 results in a downregulation of VEGF expression." (PMID 37958474, 2023). "In this study, we analyzed the expression of circRNA-000121, hsa-miR-6775, hsa-miR-4763, MMP-14, and SRC in PTMC tumor tissues and compared the levels of hsa_ircRNA_000121 and hsa_circRNA_004183 in the peripheral blood of patients." (PMID 35891968, 2022). "Divergent matrix-remodeling strategies mediated by Mmp14/MT1-MMP define the branching morphology of developing and neoplastic epithelial cells early in breast carcinogenesis." (PMID 36776368, 2022). "MMP14, which belongs to the matrix metalloproteinase (MMP) family, has an essential effect on tumor migration." (PMID 36497225, 2022). "In BCC's stroma and the peritumoral area, CAFs can secrete an array of MMPs (e.g., MMP-1, MMP-2, MMP-3, MMP-9, MMP-11, MMP-13, MMP-14, MMP-19), all of them promoting ECM remodeling and favoring tumor escape from the anti-tumoral action of the immune cells." (PMID 35572966, 2022). "Then, we analyzed the histoscores of Hsp70, Hif1α, cortactin MMP14, and MMP2 in both tumor and normal tissues and observed significantly higher expression levels of these proteins in OSCC tissues." (PMID 35957827, 2022). "MT1-MMP (which is also known as MMP14) is a proteinase located at cancer cells' membranes, and it is overexpressed in aggressive tumours." (PMID 36471888, 2022). "This analysis showed that MMP14 expression was strongly correlated with that of genes related to stromal cells (including PDGFRB and VIM) as well as that of many collagen genes, suggesting that CAFs might contribute to tumor aggressiveness associated with MMP14." (PMID 36052235, 2022). "It was found that LOXL2, PLOD2, MMP14 and SPOCK1 were upregulated in tumor samples, whereas DCN was downregulated in tumor specimens." (PMID 36186418, 2022). "The protein family of matrix metalloproteinases can degrade extracellular matrix components, whose well-known role is modulating tumor metastases, such as MMP2, MMP9, MMP7, MMP13, and MMP14." (PMID 35690612, 2022). "Several matrix metalloproteinases are expressed in melanoma, the tumor, and the peritumoral stroma, including MMP-1, MMP-2, MMP-9, MMP-13, and MMP-14." (PMID 35558554, 2022).
tumor (continued). "The treatment with the tumor soil loosening agent combined with the PD1 inhibitor significantly decreased the expression of DDR1, HIF-1α, MMP-14, and α-SMA." (PMID 36382024, 2022). "MMP-14 is upregulated in BRAF inhibitor-resistant cell lines and human tumor samples, and its upregulation is dependent on TGF-beta." (PMID 35558554, 2022). "Most DEGs in the brown module were involved in tumor progression or metastasis (module membership >0, cor = 0.83, p < 2.2e-16), including NOTCH3, VEGFA, SNAL1, TGFBR1, and MMP14, thereby confirming the correlation of some DEGs with phenotypes." (PMID 34458146, 2021). "MMP-14 degrades type I collagen, the most abundant ECM component, and modulates cell–ECM interactions, promoting cell migration and tumor invasion." (PMID 34204372, 2021). "Genes in cluster 4 associated with cancer tissue (0.83) included many oncogenes: NOTCH3 signaling promotes tumor growth in CRC, whereas MMP14 and VEGFA are correlated with poor prognosis." (PMID 34458146, 2021). "Tumor cells mitigate the immune response by releasing MMP-2, MMP-9, MMP-13 and MMP-14, resulting in the inhibition of T-cell proliferation and antigen presentation." (PMID 34204372, 2021). "The TCGA (The Cancer Genome Atlas) data also show the increased level of MMP-14 and MMP-2 in most kinds of tumor tissues." (PMID 34620867, 2021). "A novel inhibitor of TLR-2, ortho vanillin, inhibited MMP-9, MMP-14, IL-6, and iNOS expression and decreased TLR-2-mediated pro-tumor M2 phenotype of brain resident macrophages." (PMID 34439380, 2021). "We also evaluated the protein level of MMPs in our patients and measured the expression level of MMP1–MMP3, MMP7–MMP9, MMP11, MMP12, MMP14, MMP17, MMP19, and MMP28 in their tumor tissue and adjacent normal tissue by Western blot." (PMID 34804973, 2021). "MMP11, MMP14, MMP16, MMP17, MMP19, and MMP23b were positively correlated with the tumor stage, that is, the mRNA levels of MMPs in patients with higher tumor stage were always high." (PMID 34804973, 2021). "We found that MMP1, MMP3, MMP7, MMP9–MMP12, and MMP14 were significantly upregulated in tumor tissue, while MMP28 was significantly downregulated in tumor tissue." (PMID 34804973, 2021). "Although the difference between SSMs from tumor-draining and non-draining lymph nodes was not as stark as in the case of FcgR1 and FcgR4, we measured increased co-localization of MMP14 and CCL4 with CD169+ SSMs in tumor-draining nodes." (PMID 34168645, 2021). "We found that MMP1, MMP3, MMP7, MMP9-MMP12, and MMP14 were significantly upregulated in tumor tissue, while MMP15–MMP17, MMP19–MMP21, MMP23A, MMP23B, and MMP25–MMP28 were significantly downregulated in tumor tissue." (PMID 34804973, 2021). "The ZFAS1 gene is frequently amplified in HCC, which promotes metastasis through sponging tumor-suppressive miR-150 and then activating ZEB1 (zinc finger E-box-binding homeobox 1), MMP14 (matrix metallopeptidase 14), and MMP16." (PMID 34072570, 2021). "MMP14 and COL family genes are involved in tumor ECM regulation, which is very important for the study of cancer lymph node metastasis." (PMID 34094925, 2021). "Since the substrate chosen can be cleaved by MMP-14 or MMP-2, all three tumor lines appeared to be feasible for our studies." (PMID 34620867, 2021). "We therefore measured the expression of MMP14 in LUAD tissues and found that this protein is upregulated in LUAD relative to non-tumor tissues, and like MGLL, its expression is significantly correlated with overall survival." (PMID 33363004, 2020). "The GlioVis database indicated a significant increase in MMP-2, MMP-14, and MMP-9 mRNA in GBM tumor cells compared to normal tissue." (PMID 33182324, 2020). "MMP2 is involved in the degradation of tumor basement membrane and extracellular matrix, and the complex formed by MMP2 and MMP14 promotes the formation of blood vessels." (PMID 33098235, 2020).
tumor (continued). "The formation of the invadopodia that promotes the degradation of ECM by the presentation of MMP-14 and secretion of MMP-2 and MMP-9 is a fundamental event during tumor cell invasion." (PMID 33321819, 2020). "Moreover, the cancer cell-specific overexpression of membrane-type 1 matrix metalloproteinase cytoplasmic tail binding protein-1 (MTCBP-1; MMP14 binding protein inhibiting its activity) restricts metastasis in orthotopic PDAC models, further suggesting that MMP14 may enhance tumor progression." (PMID 32325664, 2020). "In patients who underwent subtotal tumor removal, tumor secreted MMP-14 and plasma MMP-14 activity were both significantly elevated compared to patients with complete tumor resection." (PMID 32848608, 2020). "Their tumor promoting activity is mediated by an increased production and activation of matrix metalloproteinases, in particular MMP9 and MMP14." (PMID 32331440, 2020). "These proteases, including MMP-3, MT1-MMP (MMP-14), cathepsin B and cathepsin D, have been reported to play important roles in cancer invasion, in vivo tumor growth and distant metastasis." (PMID 33110168, 2020). "The correlation between MMP14 and immune cell infiltration was investigated using the Cell-type Identification By Estimating Relative Subsets Of RNA Transcripts (CIBERSORT) and Tumor Immune Estimation Resource (TIMER) tools." (PMID 32974187, 2020). "MMP-14 (membrane type 1 MMP or MT1-MMP) is involved in ECM degradation, activation of MMP-13 and MMP-2 zymogen, and in molecular carcinogenesis, tumor cell growth, invasion and angiogenesis." (PMID 31086100, 2019). "We confirmed MMP-14 expression in murine GBMs and demonstrated CLIO-ICT dose-dependent inhibition of tumor growth in both xenograft and syngeneic GBM models." (PMID 31723547, 2019). "After macrophage infusion, the collagen content in tumours was significantly reduced, while the expression of MMP3, MMP14 and MMP15 was increased." (PMID 31570753, 2019). "In tumor tissue, the balance between TIMP2, MMP2 and MMP14 is tipped in favor of MMP14 and MMP2 suggesting that the levels of MMP2 activation in tumor tissue are increased." (PMID 31882975, 2019). "We found that MMP14 and HNF1A were upregulated in cancer tissues compared with the adjacent non-tumor tissues." (PMID 31810492, 2019). "We identify miR-484 as a metastasis specific suppressor with hypermethylation of promoter in CC and reveal a novel pathway in which DNMT1 epigenetically mediates miR-484 repression with resultant MMP14/HNF1A activation, which results in tumor metastasis in CC." (PMID 31810492, 2019). "The blockade of MMP-14 by IgG 3369 also disrupts the hypoxic TNBC tumor microenvironment leading to tumors with reduced density, and it impairs tumor progression and metastasis in a syngeneic breast cancer model." (PMID 31216704, 2019). "Multiple studies reported that miR-584 can function as a tumor suppressor by targeting different target genes, including WW domain-containing E3 ubiquitin protein ligase 115, ROCK116, MTDH17, PTTG1IP18, MMP-14 19 and so on." (PMID 31737116, 2019). "Since MMP-14 is overexpressed on both tumor endothelial cells and tumor cells, CLIO-ICT is activated and released in the tumor vasculature, leading to efficient breakdown of the blood brain barrier (BBB)." (PMID 31723547, 2019). "However, in our study, serum MMP-14 did not serve as a diagnostic tumor marker." (PMID 30532247, 2018). "The elevation of tumor invasion is supported by our sequencing results that demonstrated TNFα up-regulates invasion-related genes of MMP1, MMP9, MMP14, LAMB3, and FGF2 which all have been previously reported to increase OSCC cancer invasion." (PMID 30018735, 2018). "To define the consequence of MMP-14 blockade within the TME, we examined markers of tumor vasculature (CD31), hypoxia (CA9), and a marker of anti-tumor M1 tumor-associated macrophages (TAMs; iNOS)." (PMID 28938563, 2017).
tumor (continued). "Several groups have developed selective MMP-14 inhibitory antibodies that target either the catalytic domain or a collagen binding domain, and limit TNBC tumor growth and metastasis in xenograft assays." (PMID 28938563, 2017). "In the present study, the patients with double expression of MMP-14 and CD44 in their tumor had a poor prognosis." (PMID 27590006, 2016). "Since MMP14 is an activator of MMP2 and MMP9, a possible mechanism driving tumor invasion and migration is the activation of MMP2 and MMP9 through IL-6 induced MMP14." (PMID 27613828, 2016). "At the base of the invadopodia of the tumour cell, the activation of MMP-2 by MMP-14 takes place, so the observed correlation between MMP-14 and MMP-2 that has been found in other studies, is confirmed in our study." (PMID 27038607, 2016). "MMP-14 and MMP-2 expression was found in most of the tumours investigated, not only in the epithelium, but in a proportion of tumours also in the stroma." (PMID 27038607, 2016). "TIMP2 can bind to tumor cells in a specific and saturable mode; whereas, the identification of cell surface binding proteins for TIMP2 is complicated by the presence of MMP-14, which is remained poorly characterized." (PMID 26314845, 2015). "Since MMP-14 is produced by HT-1080 cancer cells, whereas MMP-11 is secreted by HFL1 stromal cells, our findings support the emerging importance of tumor-stroma interaction/cross-talk." (PMID 25081520, 2014). "The enhanced HAI-1 shedding seen in cancer cells is likely mediated by membrane-type 1 matrix metalloprotease (MT1-MMP, MMP14) that is known to be involved in the initial tumor formation and invasive growth of cancer cells." (PMID 25268161, 2014). "Considering stimulation, membrane type-1 MMP (MT1-MMP), also known as MMP14 is one of main activators, and also Interleukin-8 (IL-8) upregulates MMP2 and MMP9 in tumor cells, which is thought to be responsible for its angiogenic activity." (PMID 22695075, 2012). "Thus serum DR6 protein may serve as an indicator of tumor MMP-14 levels." (PMID 22567163, 2012). "The expression of MMP-14 and MMP-2 correlates with the depth of tumor and vascular invasion in human colon cancer." (PMID 21152183, 2011). "MT1-MMP (MMP-14) and MT2-MMP (MMP-15) both demonstrated an extremely highly significant RNA expression profile in this study, and localised to the tumour stroma." (PMID 16465195, 2006). "Animal studies showed that carcinoma cell lines transfected with MMP-14 produced higher levels of active MMP-2 and developed more lung metastases compared to parent tumor cells." (PMID 16776850, 2006). "Beyond proteolysis by the catalytic domain, the MMP-14 cytoplasmic tail engages in non-proteolytic signaling, which can activate intracellular signaling pathways in tumor cells such as ERK/MAPK, PI3K/AKT, Src, and RhoA/Rac1." (PMID 41542511, 2026). "CAV1 and MMP14 protein expression investigated by IHC increased gradually from nonbudding tumors to the bulk of budding tumors and tumor buds." (PMID 40082664, 2025). "NSC405020 acts by disrupting MMP-14 homodimerization, without having a direct effect on its catalytic activity, thus leading to increased collagen I deposition and thereby reducing tumor growth." (PMID 40869275, 2025). "While intra-tumor PpIX signals throughout GBM tumor regions were qualitatively and quantitatively lower than in extra-tumor regions, NIRF contrast from the MMP-14 targeted peptide probes remained strong throughout the GBM tumor region, including regions showing necrosis in H+E stained sections." (PMID 40093889, 2025). "Non-inferior TBR and superior tumor-specific localization of the peptide probes compared to 5-ALA supports additional development of MMP-14 targeted imaging approaches to aid assessment of GBM." (PMID 40093889, 2025).
tumor (continued). "MCT4, along with CD147, MMP14, H+ and degraded ECM, promote tumour cell invasion via vesicular transport, and high expression of GPR8 fosters glycolysis, which also contributes to tumor invasion." (PMID 40165895, 2025). "For example, we were able to identify MMP-14 with high consistency in the dECM-tumor eluates with newsECM profiling but were not able to detect any MMP-14 in the inputs with conventional bulk proteomics." (PMID 40166338, 2025). "For instance, selective MMP-9 inhibitors have shown potential in limiting tumor invasiveness and enhancing therapeutic sensitivity, while MMP-14 (MT1-MMP)-specific inhibitors have effectively restricted tumor invasion and improved the response to radiation therapy." (PMID 40265458, 2025). "Given that in non-angiogenic tumors a greater overexpression of MMP2 and MMP14 has been observed, it is of interest to inhibit these MMPs in order to reduce the aggressiveness of non-angiogenic tumor growth." (PMID 38255995, 2024). "Our findings suggest that the alteration of MMP-14 and MMP-9 levels by regorafenib may affect ECM degradation and angiogenesis, thereby suppressing tumor progression." (PMID 39199626, 2024). "Similarly, the underlying mechanisms driving TAN specialization in the tumor niche and the induction of MMP14/OPN are not well defined, but may involve activation of the TGF-β pathway, which has been shown to regulate OPN expression and synergize with MMP14 to control vessel stability." (PMID 38329810, 2024). "Macrophage-derived exosomes overexpressed MMP9 and MMP14 could degrade tumor collagens, further enhancing CD8+ T cells infiltration and the deep delivery of anti-PD-1 antibody to exert anti-tumor effects." (PMID 38644492, 2024). "Interestingly, research suggests that ACADL functions as a tumor suppressor in HCC by inhibiting metastasis via the signal transducer and activator of transcription 3 (STAT3)/Matrix Metalloproteinase 14 (MMP14) pathway." (PMID 38833109, 2024). "Thus, analyses of public patient databases and clinical specimens support our animal model findings, effectively linking MMP14/SPP1 expression and TAN presence with tumor vasculature in human cancer." (PMID 38329810, 2024). "Fibroblasts and tumor cells can secrete MMP-13, MMP-7, and MMP-14." (PMID 39247608, 2024). "Both factors have been previously associated with angiogenesis; however, we now established TANs as a major MMP14/OPN source in CRC tumors and demonstrated a specific role for each of these molecules in driving tumor vascularization via a VEGF-independent route." (PMID 38329810, 2024). "For example, MMP-14 can induce collagen I, II, and III in the tumor extracellular matrix, and MMP-2 and MMP-9 can degrade collagen IV, thus mediating tumor cell invasion into the basement membrane and inducing tumor invasion and metastasis." (PMID 39408814, 2024). "On comparison of paired tumor versus non-tumor tissue from the same livers, the fibrosis gene panel showed five genes significantly up-regulated in tumors (Pdgfb, Mmp14, Alb, Col4a1 and Pecam)." (PMID 39254423, 2024). "Fibroblasts and tumour cells secrete MMP-13, MMP-7, and MMP-14." (PMID 38911387, 2024). "Specific MMPs, including MMP2, MMP9, MMP11, MMP14, MMP15, MMP25, and MMP28, were increased in this region, indicating their distinct roles in the tumor microenvironment and confirming the importance of understanding the effects of cysteamine on specific MMPs in GBM cancer models." (PMID 38893149, 2024). "MMP14 and MMP1, members of the MMP family, can directly cleave almost all extracellular matrix components and participate in the degradation of BM and extracellular matrices, thus promoting tumor invasion and metastasis." (PMID 39085893, 2024). "As enzymes and tumour cells demonstrate the most activity at the TSI, it is reasonable to assume that ENE develops significantly in LNs involved in OSCC metastasis, wherein MMP14 is overexpressed." (PMID 36765296, 2023).